BDNF (brain derived neurotrophic factor)
Diseases named in the same sentence as BDNF in open-access papers (continued):
Sharing a sentence is not in itself a finding about the gene and the disease.
ischemic stroke (continued). "As a modulator of neurogenesis, BDNF plays important roles in neurogenesis and neuroplasticity, as well as in the self-rescue of different types of neurons after ischemic stroke." (PMID 28769792, 2017). "Simvastatin, niacin, and low-level laser therapies are known to upregulate both TrkB and BDNF and are reported to increase axonal and neurite growth in rats subjected to ischemic stroke by occlusion of the middle cerebral artery." (PMID 27313873, 2016). "We show that treadmill training intensities for ischemic stroke rats affect motor function recovery, BDNF concentration, and stress level over the 7-day intervention." (PMID 25045713, 2014). "Four BDNF tagSNPs were analyzed in the Sahlgrenska Academy Study on Ischemic Stroke (SAHLSIS; 600 patients and 600 controls, all aged 18–70 years)." (PMID 25470006, 2014). "Previous studies have demonstrated that BDNF can protect neurons against cerebral ischemic damage in animal models and against more specific insults relevant to ischemic stroke including glucose deprivation, excitotoxicity and oxidative stressors." (PMID 21949858, 2011). "The aim of this study was to investigate the effects of these three common interventions on brain BDNF changes and motor recovery levels using a rat ischemic stroke model." (PMID 21347437, 2011). "In present study, we evaluated the effect of BDNF on local cerebral inflammatory process on cellular, cytokine and transcription factor levels in ischemic stroke." (PMID 21490702, 2010). "This suggests that the protective effect of intranasal BDNF in ischemic stroke might be partially due to the downregulation of TNF-α and the upregulation of IL-10." (PMID 40895108, 2025). "Following brain damage, such as traumatic brain injury or ischemic stroke, NPCs in the dentate gyrus are activated by injury-induced signals, including growth factors like brain-derived neurotrophic factor (BDNF) and fibroblast growth factor-2 (FGF-2), as well as inflammatory cytokines." (PMID 41291782, 2025). "Therefore, therapeutic electrical stimulation improved neuronal survival in ischemic stroke by triggering NTFs such as BDNF and FGF9." (PMID 39062789, 2024). "Thus, the protective effects afforded by VPA and/or RAPA preconditioning, which involved Nrf2-modulated oxidant stress and regulation of VEGF and BDNF expression, display a simple strategy to augment cell-transplantation efficiency for ischemic stroke." (PMID 38915453, 2024). "Indeed, activation of the Akt and BDNF signaling pathways was responsible for PEMF protection against ischemic stroke in previous studies." (PMID 39684558, 2024). "In a mouse model of ischemic stroke, AAV-mVEGF-C pretreatment reduced stroke injury and ameliorated motor performances in the subacute stage, associated with mitigated microglia-mediated inflammation and increased BDNF signaling in brain cells." (PMID 38442272, 2024). "BDNF levels are significantly crucial for the recovery process in patients with ischemic stroke." (PMID 38816852, 2024). "In an ischemic stroke model in rats, a 6-week treatment with neflamapimod starting at 48 h after reperfusion accelerated the recovery of sensory and motor function, and it increased brain-derived neurotrophic factor concentration in the brain." (PMID 39339348, 2024). "Manual acupuncture (MA) at Taixi (KI3) and Taichong (LR3) can promote functional recovery as well as learning and memory abilities after ischemic stroke by enhancing BDNF and SYN expression and synaptic structural reconstruction in the ipsilateral hippocampus after I/R." (PMID 36741282, 2023). "Nape cluster acupuncture has neuroprotective and restorative effects in rats with post-ischemic stroke sequelae, and its mechanism may involve effective upregulation of BDNF and NGF protein expression." (PMID 36741282, 2023). "The findings suggested that Tdv elevated the BDNF expression in rats with ischemic stroke." (PMID 37153779, 2023).
ischemic stroke (continued). "A previous report demonstrated that serum BDNF and the BDNF-regulatory miR-124 could serve as molecular markers for acute ischemic stroke." (PMID 38034588, 2023). "Moreover, sex hormones, particularly progesterone, have been shown to increase the expression and signaling of brain-derived neurotrophic factor after ischemic stroke, with subsequent improvement in neurologic outcomes." (PMID 35522611, 2022). "In addition, BDNF was found to be an indicator of long-term functional outcomes after ischemic stroke, although the additional predictive value of BNDF was modest according to clinical data." (PMID 35572134, 2022). "Accordingly, BDNF may reduce the severity of ischemic stroke through its neurotrophic effects and its vascular protective effects." (PMID 36092813, 2022). "It shows that BDNF levels in the acute phase of ischemic stroke may possess a prognostic value for the functional status of the patient." (PMID 32944919, 2021). "We previously demonstrated that stimulation of the AT2 receptor increases the expression of BDNF in brain tissue after experimental ischemic stroke and in brain microvascular endothelial cells, resulting in improved outcomes and a proangiogenic state, respectively." (PMID 33572986, 2021). "Our current study revealed that R1 treatment significantly increased the expression of BDNF, NGF and NT-4 after ischemic stroke, and these results are similar to a previous report on the promotion of neurogenesis following the overexpression of adenoviral-transduced BDNF mRNA." (PMID 34025400, 2021). "Also, limited number of in vivo, in vitro, and in silico analysis showed the relation between miRNAs and BDNF in ischemic stroke." (PMID 32944919, 2021). "In non-diabetic patients with TIA, we also observed a complete decay of miRNA-195-5p and miRNA-451a expression 72 h after a post-ischemic stroke, paralleled by an increase in BDNF and VEGF-A levels, suggesting an attempt to preserve brain function and vascular integrity." (PMID 33076256, 2020). "Ischemic stroke induces the upregulation of BDNF and its receptor’s expression." (PMID 32916851, 2020). "This pattern of BDNF might indicate an attempt to induce neuronal recovery from the brain damage that occurs in the post-ischemic stroke period." (PMID 33076256, 2020). "Therefore, further studies are necessary to elucidate the potential role of BDNF as a GF able to induce recovery in ischemic stroke patients." (PMID 31768951, 2020). "In conclusion, DEX exerts neuroprotective in ischemic stroke via improving neuron damage, the underlying mechanism may be upregulating SHNG16 and BDNF via sponging miR-10b-5p." (PMID 32323054, 2020). "Background: brain-derived neurotrophic factor (BDNF) may play a role during neurorehabilitation following ischemic stroke." (PMID 32916851, 2020). "The aim of this study was to explore the putative role of BDNF in rehabilitation following ischemic stroke—specifically, to assess the dynamics of serum BDNF induction by the stimulation of the motor cortex by Augmented Reality (AR)-biofeedback motion training in the early recovery period." (PMID 32916851, 2020). "In the present study, we also observed an inverse relationship between BDNF and the miRNA-195-5p profile in the post-ischemic stroke period, suggesting that peaks of miRNA-195-5p and BDNF are asynchronous, thereby representing two different steps in post-ischemic neuronal repair." (PMID 33076256, 2020). "Furthermore, we have identified p-coumaric acid (P-CA) as the representative compound from AOM with the properties of promoting BDNF signaling for inducing hippocampal neurogenesis and improving functional recovery in post–ischemic stroke rat model." (PMID 33537297, 2020). "Here, we found that p‐STAT3 and BDNF levels increased in parallel to HSP70 upregulation, indicating that L‐glutamine‐induced HSP70 was involved in the proliferation of astrocytes by activating p‐STAT3 pathway and promoted the secretion of BDNF after ischemic stroke." (PMID 31218845, 2019).
ischemic stroke (continued). "However, acute BDNF administration increased microglial activation and phagocytic activity together with increased overall M2 marker expression in ischemic stroke." (PMID 31105589, 2019). "However, ischemic stroke model studies were unable to detect the presence of any BDNF mRNA, and in the case of SCI, decreased protein expression in the wound area was attributed to cell death." (PMID 31105589, 2019). "EA combined with mesenchymal stem cell transplantation may improve the recovery of neurological function and upregulate the expression of neurotrophic factors, for instance neurotrophin-4/5 (NT4) and BDNF, involved in neurogenesis in mice with ischemic stroke." (PMID 30618558, 2018). "Previously, BDNF was found to reduce inflammatory cytokines in rats following ischemic stroke." (PMID 30486515, 2018). "Furthermore, BDNF can attenuate ischemic-hypoxic injury by modulating local inflammation in rats suffering from ischemic stroke." (PMID 28778220, 2017). "On this basis, we also tested the hypothesis that DCH treatment promotes spatial cognitive function restoration after ischemic stroke by increasing neurogenesis and the BDNF level in hippocampus." (PMID 28769792, 2017). "Few clinical studies on BDNF genotypes in relation to ischemic stroke have been performed." (PMID 25470006, 2014). "BDNF gene variants were not major contributors to ischemic stroke severity, recovery, or short-term functional outcome." (PMID 25470006, 2014). "Furthermore, EPO administration after ischemic stroke or TBI increased BDNF and VEGF expression and improved functional recovery." (PMID 23675319, 2013). "On cytokine level of brain local inflammation in ischemic stroke, we found that BDNF could decrease brain TNF-α in ischemic stroke." (PMID 21490702, 2010). "This study was aimed to investigate whether brain-derived neurotrophic factor (BDNF) can modulate local cerebral inflammation in ischemic stroke." (PMID 21490702, 2010). "As early as 2017, some studies highlighted that HF-rTMS could be used to improve functional recovery in patients with ischemic stroke by enhancing neurogenesis and activating brain-derived neurotrophic factor (BDNF) and tropomyosin-related kinase B (TrkB) signaling pathways." (PMID 39268062, 2024). "It indicated that BDNF levels in the acute phase of ischemic stroke may possess a prognostic value." (PMID 38817358, 2024). "Besides, some studies found that high frequency (10–20 Hz) rTMS could promote neurogenesis in rats with ischemic stroke, and the activation of BDNF signaling pathway may be involved in the mechanism." (PMID 38570868, 2024). "Notably, rTMS, delivered after experimental ischemic stroke in animal models, may enhance neurogenesis in the hippocampus through the Brain-Derived Neurotrophic Factor (BDNF) signaling pathway." (PMID 38540283, 2024). "Thus, CEE treatment might serve as a preconditioning strategy to enhance the baseline expression of BDNF, which makes them a proper cell type for transplantation under conditions like ischemic stroke." (PMID 36631409, 2023). "Furthermore, these results suggest that MIF is neuroprotective in ischemic stroke mainly via the inhibition of apoptosis rather than through BDNF-associated mechanisms." (PMID 33672416, 2021). "Moreover, we only measured BDNF levels and only after the ischemic stroke incident had occurred." (PMID 32916851, 2020). "Interestingly, the SNP rs7124442 in the 3′-UTR of BDNF might also act as a protective factor in patients with ischaemic stroke by affecting the regulatory role of miR-922 in BDNF expression." (PMID 33029119, 2020). "Indeed, BDNF positive Tregs are upregulated compared to other BDNF positive CD4+ T-cells in the human brain following ischemic stroke, suggesting that Tregs may influence oligodendrocyte differentiation via the BDNF pathway." (PMID 31010132, 2019).
ischemic stroke (continued). "Furthermore, 3 weeks of daily 30 min exercise sessions before ischemic stroke promotes angiogenesis, increases brain-derived neurotrophic factor and midkine expression, reduces infarct volumes, neuronal apoptosis, and oxidative damage, and improves motor function but not neurological function." (PMID 30941660, 2019). "Moreover, oleandrin exhibited neuroprotective effects and protected neuronal tissues from damage, due to glucose and oxygen deprivation, dependent on the induction of brain-derived neurotrophic factor (BDNF), in brain slices and in vivo models of ischemic stroke." (PMID 31824586, 2019). "BDNF could provide protection of brain in ischemic stroke via decreasing local TNF-α." (PMID 21490702, 2010). "In summary, our data suggested that BDNF may alleviate cellular injury of ischemic insult, reduce the neurologic deficits and modulate local inflammation on cellular level, cytokine level, and transcription factor level in ischemic stroke." (PMID 21490702, 2010). "In ischaemic stroke, cGAS-STING silencing, AAV-NeuroD1-mediated neuronal reprogramming, and delivery of neurotrophic factors, including VEGF and BDNF, extend the therapeutic window well beyond reperfusion." (PMID 42193469, 2026). "FGF21’s multimodal mechanisms (neuroprotection, anti-inflammation, metabolism) and favorable safety profile make it superior to single-target growth factors (e.g., BDNF, VEGF) for ischemic stroke therapy." (PMID 40581646, 2025). "The purpose of the present study was to assess the effects of rTMS on the serum concentrations of BDNF, NGF, 5-HT, and 5-HIAA in patients with ischemic stroke." (PMID 40109842, 2025). "Elevated BDNF and NGF in peripheral blood is one of the important factors for TMS to promote cognitive function recovery in ischemic stroke patients." (PMID 40948655, 2025). "Subsequently, the expression of vascular endothelial growth factor (VEGF) and brain‐derived neurotrophic factor (BDNF) were measured, which are key neurotrophic factors for neurogenesis after ischemic stroke." (PMID 37349971, 2023). "In this study, BDNF was loaded into hNSC-Exos to construct engineered BDNF-HNSC-Exos, which were injected into the ischaemic region of an animal model of ischaemic stroke by a stereotactic method." (PMID 37553595, 2023). "Growth arrest and DNA-damage-inducible protein 45 β (Gadd45b) is associated with subventricular zone (SVZ) neurogenesis after ischemic stroke, and Gadd45b mediates enriched environment-induced SVZ neurogenesis via BDNF." (PMID 37484824, 2023). "In recent years, studies suggested ischemic stroke via several growth factors promotes neurogenesis, including FGF-2, IGF-1, BDNF, VEGF, and chemokines, including SDF-1, MCP-1." (PMID 35625017, 2022). "In OGD-induced mouse neurons and astrocytes, inhibiting miR-128 by treatment with ARPP21 antagonistic intron exhibited up-regulation of BDNF and CREB1, therefore inhibiting apoptosis and promoting neurological recovery against ischemic stroke." (PMID 35757539, 2022). "Ischemic stroke promotes neurogenesis by several growth factors including FGF-2, IGF-1, BDNF, VEGF, and chemokines including SDF-1 and MCP-1." (PMID 35035503, 2022). "Here, we sought to examine the concentrations of inflammatory cytokines (IL-1β, IL-6, and IL-10) and growth factors (VEGF, BDNF/TrkB and TGF-β) 24-h and 30 days after ischemic stroke." (PMID 34408211, 2021). "Studies showed that DPSCs can express neurotrophic factors like brain-derived neurotrophic factor (BDNF) and VEGF which have been proven to exert neuroprotection against ischemic stroke in both in vitro and in vivo experiments." (PMID 34795764, 2021). "Although the potential system and feasibility of long-term use remain to be validated, the data still suggests that daidzein promotes neuronal regeneration after ischemic stroke by upregulating Akt/CREB and enhancing BDNF expression." (PMID 35095491, 2021).
ischemic stroke (continued). "It is thought that irisin can upregulate the levels of brain-derived neurotrophic factor (BDNF), which protects nerve cells from injury during ischemic stroke." (PMID 33414714, 2020). "Serum miRNA levels, brain-derived neurotrophic factor (BDNF) and vascular endothelial growth factor A (VEGF-A) were assessed at admission and 24 and 72 h after a post-ischemic stroke, and were compared to 20 controls." (PMID 33076256, 2020). "BDNF activates intracellular tyrosine receptor kinase B, MAPK, and the extracellular signal-regulated kinases to protect against ischemic stroke." (PMID 32848639, 2020). "We found that grafted ep-iPSC-NPCs showed strong BDNF expression in vitro and in the ischemic brain, suggesting that BDNF is one of the ep-iPSC-NPC secreted factors that mediate functional recovery in ischemic stroke." (PMID 32269595, 2020). "We previously demonstrated that HUMSC transplantation treated ischemic stroke in rats primarily through the cytokines secreted by the HUMSCs, such as NAP-2, angiopoietin-2, BDNF, CXCL-16, and PDGF-AA." (PMID 31588241, 2019). "Studies suggested that BDNF and VEGF governs neurogenesis and improve functional outcomes after ischemic stroke." (PMID 31798514, 2019). "Similar to these previous studies, we also observed that BDNF was obviously induced in the hippocampus CA1 and dentate gyrus areas after LIPUS treatment in a recurrent ischemic stroke mouse mode." (PMID 31635269, 2019). "First, HDAC4 regulates the activity and expression of cAMP response element-binding protein (CREB) and brain-derived neurotrophic factor (BDNF), respectively, which play a key role in neurogenesis after ischemic stroke." (PMID 30208931, 2018). "The paracrine factors produced by BMCSs such as VEGF, BDNF, and NGF have a neuroprotective potential in animal ischemic stroke models." (PMID 27517324, 2016). "We have shown in this study that H2S preconditioned BMCSs not only have a better survival rate than controls, but also express higher levels of BDNF and VEGF, resulting in stronger therapeutic effects in ischemic stroke." (PMID 27517324, 2016). "Thus, in spite of substantial experimental evidence linking BDNF to neuronal survival, plasticity, and repair, genetic association studies so far do not lend firm support for BDNF variation as major contributor to either ischemic stroke severity or short-term recovery after ischemic stroke." (PMID 25470006, 2014). "In ischemic stroke rats, neurotrophic factors (glial cell line-derived neurotrophic factor: GDNF; brain-derived neurotrophic factor: BDNF), and vascular endothelial growth factor (VEGF) were upregulated by cortical stimulation." (PMID 25009993, 2014). "However, whether BDNF modulates inflammatory processes in ischemic stroke is unclear." (PMID 21490702, 2010). "In an experimental model of ischemic stroke, 2 reduced inflammation and increased brain-derived neurotrophic factor (BDNF) when combined with perampanel (a non-competitive AMPAR antagonist)." (PMID 40650226, 2025). "As a BDNF, PNS can increase the expression of BDNF to upregulate Akt/CREB to restore the mechanism of neurological function and promote neurogenesis and oligodendrogliogenesis after ischemic stroke." (PMID 41322290, 2025). "BDNF is a significant neurotrophic factor released by MSC, effectively delaying neuronal death, stimulating neurogenesis, and exhibiting antioxidant effects following ischemic stroke." (PMID 41154631, 2025). "The downregulation of miR-497-5p exacerbated neuronal injury in an ischemic stroke model, and this effect was mediated through the negative regulation of the BDNF/TrkB/PI3K/Akt signaling pathway." (PMID 39847586, 2025). "At the same time, no statistically significant changes in BDNF concentration were found within 14 days after ischemic stroke (p=0.503)." (PMID 36969561, 2023).